CD34 (CD34 molecule)
Diseases named in the same sentence as CD34 in open-access papers (continued):
Sharing a sentence is not in itself a finding about the gene and the disease.
multiple myeloma (continued). "By this way we reproduced our experimental condition setting, which includes a mixed population of healthy CD34+ cells and myeloma cells." (PMID 17626627, 2007). "Available clinical evidences suggest that CD34+ selection reduces myeloma contamination in PBSC (Peripheral Blood Stem Cell) collections, however, it does not eliminate it, and it does not improve disease-free or overall survival of transplanted patients." (PMID 17626627, 2007). "This innovative combined procedure exploits the gene transfer technique to enrich for high repopulating-capacity CD34+ cells, and, at the same time, to eliminate myeloma contaminants." (PMID 17626627, 2007). "When we amplified DNA from mobilized aphereses, 83.3% of samples showed detectable myeloma contaminants, and 77.8% of the samples still retained myeloma cells after CD34+ antigen selection (gray shaded cells)." (PMID 17626627, 2007). "Myeloma plasma cells exhibit a high mortality in culture (50–95% in 9 days); we exploited this biological behaviour to perform a culture-based purging of myeloma CD34-selected leukaphereses." (PMID 17626627, 2007). "We cultured myeloma-positive CD34+ PB samples in conditions that retained multipotency of hematopoietic stem cells, but were unfavourable to survival of plasma cells." (PMID 17626627, 2007). "There is also a tendency of myeloma contaminants to further decrease after transduction and selection of CD34+ cells, as compared with the simple culture." (PMID 17626627, 2007). "After ex-vivo cytokine culture, 57.1% (4 out of 7) tumor-positive CD34+ samples lost myeloma specific rearrangements (MM6,14,18,19), with an estimation of 0 to >2.35 logs purging, with respect to the initial tumor load." (PMID 17626627, 2007). "The International Myeloma Working Group has suggested a minimum target of 4 × 10^6 CD34 +/kg and, if feasible, an average of 8 − 10 × 10^6 CD34 +/kg should be collected, allowing most myeloma patients to undergo two autografts during the course of their disease." (PMID 40911111, 2025). "Autologous transplantation remains the standard of care for eligible multiple myeloma (MM) patients, yet optimal CD34+ cell dose remains unclear." (PMID 39482325, 2024). "As shown, patients who received biosimilar Peg-filgrastim were significantly older (p < 0.001), more frequently affected by myeloma and then treated with melphalan-based conditioning regimens (p = 0.004) and were infused with a significantly lower number of CD34 + cells (p < 0.001)." (PMID 38189833, 2024). "A prospective trial at MD Anderson Cancer Center assessed the impact of CD34+ cell dose on the outcomes of patients with MM (73%) or light chain amyloidosis who underwent auto-HCT and received either a standard (4–6 × 106 CD34+ cells/kg) or high-dose (10–15 × 106 CD34+ cells/kg)." (PMID 39482325, 2024). "It was capable of mobilizing hematopoietic stem cells with the CD34 marker, so it has been approved by the US Food and Drug Administration for autologous transplantation of bone marrow cells in patients with non-Hodgkin's lymphoma or multiple myeloma 39-41." (PMID 34976180, 2022). "Interestingly, compromised stainability of CD34 cells with the hematology analyzer were reported among myeloma patients due to the unspecific labelling." (PMID 36289245, 2022). "This study investigated the cost and effectiveness (i.e., successful 4 million-CD34+ collection) of G-CSF alone versus high-dose cyclophosphamide (4 g/m2) + G-CSF mobilization (± on-demand plerixafor) in patients with multiple myeloma (MM) eligible for autograft in Italy." (PMID 33753907, 2021). "Myeloma cases are more common in older patients with an average age of 67 and reduced engraftment has been observed in patients of 70+ years, particularly with respect to CD34+ cells." (PMID 33104704, 2020).
multiple myeloma (continued). "The P2RX5 gene is expressed in normal lymphocytes, B and T lineage ALL, a range of lymphoma and multiple myeloma cases, the CD34+ fractions of CML and AML, and possibly at low levels in brain and skeletal muscle, but there is minimal expression in GVHD target tissues (intestine, liver, lung, skin)." (PMID 32582592, 2020). "Importantly, blocking the CCL3 signal with BX471 (an antagonist of CCR1) effectively restored the effect of CCL3 on the downregulation of the transcription factor GATA1 in CD34+ cells in the myeloma microenvironment." (PMID 33239656, 2020). "Clinical trials with BL-8040 and G-CSF (a glycoprotein that induces stem cell mobilization by decreasing bone marrow SDF-1 and up-regulating CXCR4) have shown a significant increase in CD34+ cell mobilization from the bone marrow for patients that require autologous transplant in myeloma." (PMID 32658899, 2020). "Interestingly, we found that a high level of CCL3 significantly suppressed GATA1 expression at both the mRNA and protein levels in CD34+ cells in myeloma bone marrow." (PMID 33239656, 2020). "Furthermore, a colony formation assay of CD34+ HSPCs from myeloma patients or healthy control subjects was performed." (PMID 33239656, 2020). "Therefore, after confirming that approximately 75% of CD34+ mobilized peripheral blood progenitor cells from myeloma patients en route to SCT co-expressed CD38, we sought to determine the number of CD38 molecules per CD34+ cell." (PMID 30356940, 2018). "We next investigated whether eltrombopag is capable of stimulating megakaryopoiesis in purified CD34+ cells isolated from patients with relapsed multiple myeloma (n = 5)." (PMID 25886818, 2015). "We examined the effects of eltrombopag on megakaryocyte colony-forming capacity in CD34+ cells in patients with multiple myeloma and investigated its impact on proliferation, viability, and apoptosis in primary CD138+ human myeloma cells and myeloma cell lines." (PMID 25886818, 2015). "Therefore, 2–4 × 106 CD34+ cells/kg body weight were recently defined as minimum and 8–10 × 106 CD34+ cells/kg bw as optimum dose for autologous (tandem) transplantation in patients with multiple myeloma (MM)." (PMID 25165572, 2014). "Moreover, RENIN and ANGTS mRNA expression levels were significantly higher in CD34+ stem cell samples of healthy allogeneic donors compared to those in myeloma patients (p=0.001 and p=0.01)." (PMID 25035670, 2014). "Silencing during differentiation of CD34 positive cord blood cells closed respective chromatin while treatment of myeloma cells with an IRF4 transcriptional inhibitor opened a site to DC-PCR that was occupied by RNA polymerase II and NFκB as determined by ChIP." (PMID 22984542, 2012). "Similarly CD133+CD34+ cells exhibit a strong correlation with degree of engraftment in multiple myeloma patients undergoing autologous transplantation." (PMID 21219665, 2011). "We hypothesised that varying levels of mobilised CD34+ cells confer prognostic information in myeloma patients undergoing high-dose chemotherapy." (PMID 21878938, 2011). "A total of 158 consecutive myeloma patients undergoing autologous transplantation during their first-line treatment were stratified into two groups based on the level of circulating peripheral CD34+ cells at the day of stem cell collection." (PMID 21878938, 2011). "Mononuclear cells, CD34+ fresh cells, cytokines-cultured cells, and ΔLNGFR-positive and -negative selected fractions were analyzed in 10 experiments, and DNA was amplified for myeloma specific clonal rearrangements." (PMID 17626627, 2007). "To exclude the presence of myeloma "long-living" contaminants, or possible myeloma precursors in the transduced and selected cell fraction, we seeded CD34+/ΔLNGFR+ cells of patient MM18 in a LTMC assay, adding IL6 to the culture to favour the maintenance of the plasma cells in culture." (PMID 17626627, 2007).
multiple myeloma (continued). "Therefore, in this study, we only demonstrated that ALKBH5 increased the percentage of SP cells and CD138-/CD34- myeloma stem cells by activating cancer stem cell related HIPPO pathway signalling and promoting the expression of pluripotency factors NANOG, SOX2 and OCT4." (PMID 35414790, 2022). "However, we did not observe any association between osteopontin levels and CD34+ cell mobilization/yield, neither in the myeloma patients, nor in the healthy stem cell donors." (PMID 27447610, 2016). "Like CD31, CD34 has been proposed as a sensitive marker for endothelial cells, has been used to diagnose vascular tumors, and has been used to evaluate the degree of angiogenesis in a variety of neoplasms, including cervical cancer, prostate cancer, and multiple myeloma." (PMID 25881913, 2015). "Moreover myeloma cells display a very low retroviral-mediated transduction rate, even after repeated infection cycles (1.5–5.4%), therefore we structured the protocol to allow the insertion and the expression of retroviral genes in the CD34+ cells." (PMID 17626627, 2007). "Moreover, we exploited the resistance of myeloma plasma cells to retroviral transduction by targeting the hematopoietic CD34+ cell population with a retroviral vector carrying a selectable marker (the truncated form of the human receptor for nerve growth factor, ΔNGFR)." (PMID 17626627, 2007). "A phase 3 clinical trial in 2001 aimed on purging of autologous peripheral-blood stem cells using CD34 selection demonstrated that CD34 selection could significantly reduce myeloma cell contamination in SCC, but it did not reduce the risk of disease progression." (PMID 37679605, 2023). "In vivo studies conducted in irradiated NOD/SCID mice, which were simultaneously injected with CD34+ HSC and myeloma cells indicated that the occupation of HSC in the BM niche decreased as the number of myeloma cells injected increased." (PMID 36072809, 2022). "LRH-1-specific T cells kill ALL CD34+, AML CD34+, CML CD34+, and multiple myeloma CD138+ cells in vitro." (PMID 32582592, 2020). "Our data showed that the frequency of LT-HSCs (Lin−, c-kit+, Sca-1+, CD34−, CD135-) in the bone marrow of the myeloma mouse model was notably increased compared to that in control mice (21.13% ± 0.85% vs. 7.55% ± 1.46%, p < 0.0001)." (PMID 33239656, 2020). "We determined that approximately 75% of CD34+ mobilized peripheral blood progenitor cells from myeloma patients en route to SCT co-expressed CD38, and then sought to determine the number of CD38 molecules per CD34+ cell." (PMID 30356940, 2018). "In view of the role of autologous SCT in patients with multiple myeloma, we investigated CD38 expression on mobilized CD34+ cells from myeloma patients and the binding and effect of daratumumab on mobilized CD34+ cells in vitro." (PMID 30356940, 2018). "In this study, CD34+MM hematopoietic cells also locally expressed RENIN, ANGTS, and ACE I mRNA, indicating the activity of RAS in myeloma-related progenitor cells." (PMID 25035670, 2014). "Overall recovery of CD34+ cells after culture was 128.5%; ΔNGFR transduction rate was 28.8% for CD34+ cells and 0% for CD138-selected primary myeloma cells, respectively." (PMID 17626627, 2007). "To assess the transduction rate of myeloma cells, we infected BM CD34+ cells of a MM patient, after adding back to the cell population CD138+ myeloma plasma cells sorted from the same patient (ratio 1:1)." (PMID 17626627, 2007). "Human CD34+ hematopoietic progenitor cells were isolated from the BM of patients with multiple myeloma and differentiated to MKs with or without S100A9." (PMID 36923707, 2023). "CD34 is expressed in hematopoietic precursor and mature endothelial cells in human, but it is not thought to be expressed in myeloma cells or tissue." (PMID 37120508, 2023).
multiple myeloma (continued). "The International Myeloma Working Group (IMWG) recommends that an average of 8 × 106 CD34+ cells/kg should be given if mobilized, and that the minimum administration target should be 4 × 106 CD34+ cells/kg progenitor cells for auto-HCT eligible MM patients." (PMID 36949293, 2023). "B-cell maturation antigen (BCMA) is widely expressed on plasma cells, myeloma cell lines, and primary myeloma while absent in primary human CD34+ hematopoietic cells." (PMID 34422667, 2021). "This increase in PDIA1 confers its sensitivity to CCF642-34, a structurally optimized PDIA1 inhibitor that induces apoptosis in myeloma cells but not in normal bone-marrow-derived CD34+ hematopoietic stem and progenitor cells." (PMID 34071205, 2021). "The inhibition of PDIA1 overwhelms the UPR in myeloma cells, resulting in their apoptotic cell death at doses that do not affect the normal CD34+ hematopoietic stem and progenitor cells." (PMID 34071205, 2021). "Large patient-to-patient variations were observed as is not uncommon in myeloma patients e.g. trypan blue dye exclusion ranged from 38% to 100% and CD34+ viability from 8% to 87%." (PMID 33104704, 2020). "The International Myeloma Working Group (IMWG) recommends that an average of 8 × 106/kg CD34+ should be given if mobilized, and that the minimum administration target should be 4 × 106/kg CD34+ progenitor cells." (PMID 32512672, 2020). "The second generation of MSCs of multiple myeloma showed no expression of surface markers of hematopoietic cells, such as CD34 and CD45, and displayed low expression of CD106, high expression of CD29, and the surface markers of MSCs (CD105)." (PMID 31548362, 2019). "Because mobilized CD34+ cells are critical for stem cell transplant, we investigated the in vitro activity of daratumumab on mobilized CD34+ cells from myeloma patients with no prior exposure to daratumumab." (PMID 30356940, 2018). "Interestingly, CCF642-34 is 20-fold more potent in restricting the colony-forming abilities of MM cells, RPMI-8226, compared to its effect on the clonogenic potential of CD34+ HSPCs derived from healthy bone marrow, supporting PDIA1 as a target with favorable therapeutic index in multiple myeloma." (PMID 34071205, 2021). "Importantly, only activated and expanded NK cells were able to kill autologous myeloma cells in vitro, without any cytotoxicity against autologous CD34+ cells." (PMID 30542346, 2018). "In vitro, daratumumab is not toxic to mobilized CD34+ progenitor cells from myeloma patients." (PMID 30356940, 2018). "A still not well defined proportion of patients with multiple myeloma (MM) and eligible for autologous stem cell transplantation (AuSCT) fails to mobilize CD34+ peripheral blood stem cells (PBSC) at all or to collect an adequate number for a safe procedure or sufficient for multiple transplants." (PMID 25889496, 2015). "Our preclinical study provides proof-of-principle demonstrating that eltrombopag is capable of stimulating megakaryopoiesis in CD34+ cells from patients with relapsed multiple myeloma and does not promote proliferation of human primary multiple myeloma cells or myeloma cell lines." (PMID 25886818, 2015). "However, we did not observe in our cohort of myeloma patients undergoing autologous transplantation that the number of CD34+ cells infused at transplantation affected OS or TTP, with P=0.754 and P=0.899, respectively, for patients below vs above the mean value of infused CD34+ cells." (PMID 21878938, 2011). "Although previous studies indicated that patients with various lymphoid malignancies mobilising large numbers of CD34+ cells (‘super mobilisers’) enjoy improved survival following autologous stem cell transplantation, such data are lacking so far for myeloma patients." (PMID 21878938, 2011).
multiple myeloma (continued). "Our results further demonstrated that the number of HPCs (Lin-CD34+CD38+), but not HSCs (Lin-CD34+CD38−), was more significantly decreased in the bone marrow of myeloma and negatively correlated with the quantity of CD38+CD138+ tumour cells (r = − 0.6112)." (PMID 33239656, 2020). "Both HD-ASC and MM-ASC expressed very low levels of CD34, while CD38 expression was negative in both cases, indicating that the cell cultures contained no myeloma cells (data not shown)." (PMID 31083455, 2019).
glioma (70 papers, 2010 to 2025). A benign or malignant brain and spinal cord tumor that arises from glial cells (astrocytes, oligodendrocytes, ependymal cells). "The high expression of vascular density marker CD34 in gliomas is associated with high-grade gliomas, leading to its application as a potential diagnostic and prognostic marker for glioma patients." (PMID 39065567, 2024). "The results showed that higher expression levels of CD31 and CD34 were associated with increased vascularity and angiogenesis in low-grade gliomas." (PMID 38089632, 2023). "Although linear capillaries and circular tubular structures formed by CD34+ cells were observed in the glioma samples, the associated lumen was thin and the tube wall was rough." (PMID 31960509, 2020). "Increased CD34 expression has been associated with new blood vessel growth and has been found in high-grade gliomas." (PMID 33168005, 2020). "CD34 expression in glioma tissues was shown to be closely associated with high WHO grades (III + IV; SMD -1.503, 95% CI: -1.685 to -1.321; P = 0.000)." (PMID 26886640, 2016). "CD34 overexpression in glioma tissues was associated closely, according to the pooled SMD, with higher WHO grade (III + IV) (SMD -1.503, 95% CI -1.685 to -1.321; P = 0.000)." (PMID 26886640, 2016). "CD34 expression was reported in 12 glioma studies and the association with WHO grades in 684 patients was investigated." (PMID 26886640, 2016). "Moreover, the density of CD34-stained microvessels is closely associated with clinical progression and survival outcomes in glioma patients." (PMID 40892951, 2025). "Beside grading, CD34 expression might of assistance to indicate glioblastoma stem-like cells differentiation into tumor-associated endothelial cells in low-grade gliomas." (PMID 31968004, 2020). "Our results suggested that CD34 overexpression is associated with higher WHO grades of gliomas." (PMID 26886640, 2016). "Experimental evaluation on a curated glioma CD34 dataset demonstrates that PGE-Net achieves notable improvements over ResNet18 baselines, with Precision, Recall, and F1-score increased by 9.17%, 9.35%, and 12.35%, respectively." (PMID 40892951, 2025). "Glioma diagnosis and prognosis heavily rely on immunohistochemistry (IHC), particularly CD34-stained images which highlight tumor vascular endothelial cells." (PMID 40892951, 2025). "Compared to other tissue types, such as breast cancer, CD34 staining in glioma tissue often exhibits a higher degree of spatial heterogeneity and irregular staining patterns, making image segmentation and feature extraction more challenging." (PMID 40892951, 2025). "Under the condition of hypoxia or glucose deficiency, glioma stem cells can express CD31 and CD34 and participate in angiogenesis." (PMID 39744577, 2025). "A significant increase in serum VEGFA concentration and tumor CD34 expression was observed in IDO1-overexpressing GL261 subcutaneous glioma-bearing mice." (PMID 39065567, 2024). "Immunohistochemistry staining was employed to determine the expression levels of IDO1, VEGFA, and CD34 in paraffin-embedded tissue sections obtained from 5 non-glioma tissue donors and 13 glioma tissue donors." (PMID 39065567, 2024). "Bioinformatic analyses showed that the expressions of IDO1 and angiogenesis markers VEGFA and CD34 were positively correlated and increased with pathological grade in glioma." (PMID 39065567, 2024). "At the same time, we collected the immunohistochemical and genetic detection results of glioma patient samples, including Vimentin, S-100, GFAP, SYN, EMA, CD34, Ki67, IDH mutation, MEMG methylation and 1p/19q lost and other information." (PMID 36831736, 2023). "CD34 was only rarely observed in GBMs and other gliomas in our study, with the exception of GGs; this limits its practical use." (PMID 37568909, 2023). "CD34-positive hematopoietic stem cells were reported in glial tumours and also in subsets of proliferating microglias of rat models of amyotrophic lateral sclerosis." (PMID 37568909, 2023).